ELK4 (ETS transcription factor ELK4)
Description:
Involved in both transcriptional activation and repression. Interaction with SIRT7 leads to recruitment and stabilization of SIRT7 at promoters, followed by deacetylation of histone H3 at 'Lys-18' (H3K18Ac) and subsequent transcription repression. Forms a ternary complex with the serum response factor (SRF). Requires DNA-bound SRF for ternary complex formation and makes extensive DNA contacts to the 5'side of SRF, but does not bind DNA autonomously.
Synonyms: SAP1
Tractability: PROTAC: UniProt records ubiquitination sites on it; ubiquitination databases record sites on it.
Gene: Protein-coding gene on chromosome 1 (205,597,556 to 205,634,520, reverse strand). Ensembl gene ENSG00000158711.
Subcellular location: Nucleus
Subcellular location (Human Protein Atlas): Nucleoplasm
Gene Ontology:
Molecular function: chromatin binding; DNA-binding transcription activator activity, RNA polymerase II-specific; protein binding; RNA polymerase II cis-regulatory region sequence-specific DNA binding; sequence-specific double-stranded DNA binding; DNA binding; DNA-binding transcription factor activity; DNA-binding transcription factor activity, RNA polymerase II-specific; sequence-specific DNA binding
Biological process: negative regulation of transcription by RNA polymerase II; positive regulation of transcription by RNA polymerase II; cell differentiation; regulation of transcription by RNA polymerase II; negative regulation of DNA-templated transcription; regulation of DNA-templated transcription
Cellular component: nucleoplasm; chromatin; nucleus
Genetic constraint (gnomAD): Loss-of-function variants: 16 observed, 28.38 expected, observed/expected ratio (o/e) 0.56, 90% interval 0.38 to 0.86. The upper end of that interval is the gene's LOEUF score, 0.86, which puts it in group 3 of 6, group 1 being the genes least tolerant of losing a copy. Missense variants: 456 observed, 522.98 expected, observed/expected ratio (o/e) 0.87, 90% interval 0.81 to 0.94. Synonymous variants: 208 observed, 198.41 expected, observed/expected ratio (o/e) 1.05, 90% interval 0.94 to 1.18.
Cancer hallmarks: proliferative signalling (promotes); escaping programmed cell death (promotes)
Homologues: Orthologues: chimpanzee ELK4 (99% identical), macaque ELK4 (98% identical), guinea pig ELK4 (88% identical), mouse Elk4 (87% identical), rabbit ELK4 (86% identical), rat Elk4 (86% identical), dog ELK4 (86% identical), pig ELK4 (84% identical), tropical clawed frog elk4 (60% identical), zebrafish elk4 (55% identical). Paralogues in human: ELK3 (48% identical), ELK1 (36% identical), ERF (22% identical), ETV3 (20% identical), ELF2 (19% identical), ELF4 (19% identical), FLI1 (19% identical), ERG (19% identical), FEV (17% identical), ERFL (17% identical), ELF1 (16% identical), ETV3L (16% identical), and 16 more.
Diseases named in the same sentence as ELK4 in open-access papers:
ELK4 is named in the same sentence as 48 diseases in open-access papers, as found by Europe PMC text mining. Sharing a sentence is not in itself a finding about the gene and the disease. The quoted sentences say what the papers report.
prostate carcinoma (32 papers, 2011 to 2025). A carcinoma that arises from epithelial cells of the prostate gland. "A well-characterized example is the cis-SAGe between SLC45A3 and the ETS transcription factor ELK4 in prostate cancer." (PMID 41155268, 2025). "ELK4 protein plays a crucial role in controlling cell overgrowth, operating in both androgen-dependent and -independent prostate cancer cells." (PMID 38136890, 2023). "One example is the well-studied cis-SAGe fusion between solute carrier family 45 member 3 (SLC45A3) and the ETS transcription factor ELK4 found in prostate cancer." (PMID 36527429, 2023). "ELK4 is involved in the development of prostate cancer by regulating the chimeric fusion SLC45A3-ELK4 transcript." (PMID 34372882, 2021). "ELK4 is a transcription factor associated with the MAPK family and has been shown to be a prognostic indicator in prostate cancer." (PMID 33450975, 2021). "So far, the most studied one in prostate cancer is the one where SLC45A3 is involved in the generation of a chimeric transcript with ELK4." (PMID 33634124, 2021). "Only a few reports describe a putative functional impact of read-throughs on cancer with the most convincing one reported for SLC45A3-ELK4 in prostate cancer, where the read-through promotes cell proliferation but wild-type ELK4 does not." (PMID 25888189, 2015). "The fact that androgen signaling blockadein the case of prostate cancer reduced telomerase activity indirectly provesthat ELK4 participates in the regulation of TER transcription." (PMID 25093110, 2014). "ELK4 is involved in cell growth promotion and is found to be overexpressed in prostate cancer." (PMID 38173042, 2024). "SLC45A3-ELK4 lnccRNA was found to be <1% of the expression level of the native ELK4 mRNA and therefore would only contribute to a minor percentage of the total ELK4 protein pool in prostate cancer cells." (PMID 33634124, 2021). "Thus, the functional consequences of these ELK4 fusions and whether they contribute to prostate cancer pathogenesis in a manner similar to that of other ETS fusions remain to be determined." (PMID 35943799, 2022). "In this cohort, we identify mirrored-subclonal copy-number aberrations in all 10 of these cases, including parallel amplification of ELK4 and SLC45A3 which comprise a chimeric transcript known to be related to cell proliferation in prostate cancer." (PMID 38773520, 2024). "Conversely, some lineage-specific genes are seen to serve as 5′ partners across multiple different 3′ genes; for example, TMPRSS2 and SLC45A3 in prostate cancer have been observed as 5′ partners of ERG, ETV1, ETV4, ETV5, BRAF, and ELK4." (PMID 26684754, 2015). "When SLC45A3-ELK4, but not ELK4 is silenced, the proliferation of prostate cancer cells is inhibited." (PMID 36527429, 2023). "In some prostate cancer cell lines, environmental factors can change the expression level of FuTAG SLC45A3-ELK4, located on chromosome 1q32 and composed by the first exon of SLC45A3 and the last four of ELK4 (Type II ISP or Co-TIFE); despite this, the ELK4 is translated as a wild type protein." (PMID 31652751, 2019). "For example, “read-through” chimeric SLC45A3-ELK4 transcripts, such as those detected in prostate cancer, result from runaway transcription of the androgen-inducible, prostate-specific gene SLC45A3 into ELK4, the adjacent ETS family gene in the same orientation." (PMID 26684754, 2015). "Notably, the chimeric mRNA, but not the wild-type ELK4, was identified as a driver for androgen-dependent proliferation in prostate cancer cells." (PMID 38136890, 2023). "Moreover, the SLC45A3-ELK4 transcript was shown to be induced by androgens and the chimeric mRNA, but not the wild-type ELK4, was found to drive androgen-dependent proliferation in prostate cancer cells." (PMID 33634124, 2021).
prostate carcinoma (continued). "ELK4 was expressed as a major type among the ELK profiles in bladder carcinoma, cervical tumor, chondrosarcoma, colorectal tumor head and neck tumor, kidney tumor leukemia, lung tumor, lymphoma, ovarian tumor, prostate cancer, skin cancer, and soft tissue/muscle tissue tumor." (PMID 31018569, 2019). "Also, the chimeric transcript SLC45A3-ELK4, generated by cis-splicing between the adjacent SLC45A3 and ELK4 genes, did not involve DNA rearrangements or trans-splicing and could augment prostate cancer cell proliferation." (PMID 29499655, 2018).
gastric cancer (9 papers, 2021 to 2025). A primary or metastatic malignant neoplasm involving the stomach. "ELK4, recognized as a proto‐oncogene, has been linked to the aggressive characteristics of glioblastoma, gastric cancer, and skin cutaneous melanoma." (PMID 39969091, 2025). "ELK4 has been identified as a proto-oncogene whose overexpression was associated with the malignant phenotypes of prostate, melanoma, and gastric cancers." (PMID 35526007, 2022). "In gastric cancer cells and tumor associated macrophages, ELK4 might possibly activate lysine-specific demethylase 5A (KDM5A), which inhibits the expression of Praja 2 (PJA2), thus decreasing kinase suppressor of Ras 1 (KSR1)." (PMID 37381723, 2023). "In gastric cancer, ELK4 activates lncRNA SNHG22 transcription to inhibit tumor suppressor expression and upregulate the Notch1 signaling, facilitating cell proliferation and invasion." (PMID 41502523, 2025). "In gastric cancer, ELK4 plays a role in regulating the lysine-specific demethylase 5 (KDM5A)/Praja-2 (PJA2)/kinase suppressor of RAS1 (KSR1) axis." (PMID 37381723, 2023). "In addition, ELK4 plays a key role in many cancers, and its overexpression is related to the malignant phenotype of colorectal cancer and gastric cancer." (PMID 39969091, 2025). "The authors of this study found that the transcription factor ELK4 (ETS transcription factor ELK4) binds to the promoter region of the SNHG22 and promotes its expression in gastric cancer cells." (PMID 38473229, 2024). "We tried to elaborate the molecular mechanism of ETS-like transcription factor 4 (ELK4) affecting gastric cancer (GC) progression through M2 polarization of macrophages mediated by lysine-specific demethylase 5A (KDM5A)-Praja2 (PJA2)-kinase suppressor of ras 1 (KSR1) axis." (PMID 34372882, 2021).
colorectal cancer (7 papers, 2020 to 2025). A primary or metastatic malignant neoplasm that affects the colon or rectum. "One study of colorectal cancer reported that LAMB3 overexpression was activated by BRD2/acetylated ELK4 complex; furthermore, LAMB3 overexpression activated AKT and resulted in degradation of FOXO3/4, a tumor suppressor protein." (PMID 38473784, 2024). "We and others have demonstrated that ELK4 is overexpressed in various cancers, including colorectal cancer and melanoma, and is required for cancer cell proliferation." (PMID 37529050, 2023). "In previous studies, LAMB3 was also reported to promote tumor progression and chemoresistance through the AKT-FOXO3/4 axis and be transcriptionally regulated by the BRD2/acetylated ELK4 complex and polymeric immunoglobulin receptor in colorectal cancer." (PMID 36612197, 2022). "Moreover, MEK inhibitor U0126 exhibits a synergetic effect with BET inhibitor JQ1 via ELK4 activity inhibition in colorectal cancer." (PMID 33585247, 2020). "In colorectal cancer (CRC), PYCR1 is phosphorylated at Tyr‐135 by nuclear IGF1R under hypoxia, which promotes its binding to ELK4 and recruitment to gene promoters." (PMID 39422696, 2024). "For instance, transcriptional activation of ELK4 target genes could be inhibited by JQ1, a BET inhibitor, via disrupting the interaction between ELK4 and BRD2 in colorectal cancer." (PMID 33585247, 2020).
melanoma (5 papers, 2015 to 2023). A malignant, usually aggressive tumor composed of atypical, neoplastic melanocytes. "ELK4 is regarded as an oncogenic gene in several cancers, such as melanoma, prostate, gastric, and lung cancers." (PMID 36556251, 2022).
glioblastoma (4 papers, 2021 to 2025). The most malignant astrocytic tumor (WHO grade IV). "ELK4-mediated Mcl-1 overexpression promotes oncogenesis in glioblastoma." (PMID 41502523, 2025). "Additionally, a previous study found that ELK4 is correlated with the survival of glioblastoma patients and thus serves as a potential prognostic marker." (PMID 34372882, 2021).
lung cancer (4 papers, 2011 to 2025). A malignant neoplasm involving the lung. "We found omentin to be consistently downregulated in lung cancers, and it exhibited a negative correlation with important transcription factors FOXA1, EN1, FOXC1 and ELK4." (PMID 33450975, 2021).
prostate tumor (3 papers, 2011 to 2019). "Quantitative RT-PCR analyses confirm that the expression of ELK4 exon 2 (sum of fusion and wildtype) is significantly higher than that of exon 1 (wildtype) in 39 prostate tumor samples (p = 3.1E-10, Wilcoxon rank-test)." (PMID 28467780, 2017). "We found that the 5' gene SLC45A3 is expressed specifically in prostate tumor and normal samples, whereas the 3' gene ELK4 is expressed broadly across multiple tissues." (PMID 21261984, 2011). "Previous studies demonstrated that a fusion transcript named SLC45A3-ELK4 was formed with exon 1 of SLC45A3 and the last 4 exons of ELK4, which acted as oncogenes in prostate tumor cells without chromosomal changes." (PMID 31057610, 2019).
Vestibular schwannoma (3 papers, 2021 to 2025). A vestibular schwannoma (also known as acoustic neuroma, acoustic neurinoma, or acoustic neurilemoma) is a benign, usually slow-growing tumor that develops from the VIIIth cranial nerve supplying the inner ear. "Conversely, ELK4 functions as a tumor suppressor in vestibular schwannoma by promoting HCG11 transcription, thereby inhibiting cell proliferation and inducing apoptosis." (PMID 41502523, 2025). "The rescue assays illustrated the effectiveness of HCG11/miR-620/ELK4 axis in vestibular schwannoma." (PMID 33402177, 2021).
asthma (2 papers, 2023 to 2024). "Additionally, the area of the bronchiole wall (Wa) and the perimeter of the bronchiole basement membrane were semiquantitatively analyzed, which showed that the Wa/Pbm ratio in the Elk4-deficient mice was significantly lower than that in WT mice with asthma." (PMID 37529050, 2023). "Consistent with the observations in the skin tissue, the number of mast cells in the lung tissue from Elk4 KO mice was much lower than that in lung tissue from WT mice with asthma." (PMID 37529050, 2023). "Similarly, MUC5AC was expressed at higher levels in WT mice than in Elk4 KO mice with asthma." (PMID 37529050, 2023).
head and neck squamous cell carcinoma (2 papers, 2021 to 2025). A squamous cell carcinoma that arises from any of the following anatomic sites: lip and oral cavity, nasal cavity, paranasal sinuses, pharynx, larynx, and salivary glands. "Although ELK4 has been implicated as a potential regulator in head and neck squamous cell carcinoma, its function in OSCC remain unexplored." (PMID 41502523, 2025).
osteoporosis (2 papers, 2016 to 2022). A condition of reduced bone mass, with decreased cortical thickness and a decrease in the number and size of the trabeculae of cancellous bone (but normal chemical composition), resulting in increased fracture incidence. "For the TFBSs, we identified 2 TFBSs (EZH2 and RAD21) for enrichment, and 2 TFBSs (ELK4 and HDAC1) for depletion in the promoters of osteoporosis-associated genes, respectively." (PMID 27465306, 2016). "Our research uncovered an exosomal miR-92b-3p/ELK4 signaling pathway that regulated osteoblast differentiation, suggesting that exosomes may be a promising therapeutic strategy for disuse osteoporosis." (PMID 36556251, 2022).
Atrophy (1 paper, 2023). Any weakening or degeneration, especially through lack of use. "From our hierarchical atlas of atrophy-related TFs, we recognized that ELK4, an ETS domain-containing TF, occupies the highest tier, implying that it could be a hub in regulating muscle atrophy." (PMID 37853001, 2023).
breast carcinoma (1 paper, 2017). "A transcriptional enhancer in the G allele of rs554219 increases the risk of breast cancer by reducing the binding of ELK4 transcription factor and correlates with low cyclin D1 levels in breast cancer tissues." (PMID 29299175, 2017).
cervical cancer (1 paper, 2025). A primary or metastatic malignant neoplasm involving the cervix. "In HPV-positive cervical cancer, ELK4 promotes cell cycle progression and stemness by modulating the FBXO22/PTEN axis." (PMID 41502523, 2025).
colon tumors (1 paper, 2023). "We found that compared with their wild‐type littermates, Elk4−/− mice exhibited significant decreases in the number and size of colon tumors after AOM‐DSS administration." (PMID 37786278, 2023).
epilepsy (1 paper, 2021). A brain disorder characterized by episodes of abnormally increased neuronal discharge resulting in transient episodes of sensory or motor neurological dysfunction, or psychic dysfunction. "It should be noted, however, that the ETS expression profile is also different in epilepsy; ELF1, ELK1, ELK4, ETS1, ETS2, and ETV1 are expressed at higher levels than ELF4, ELK3, and ETV4, and there is also variability in expression among different types of epilepsy." (PMID 33671331, 2021).
fungal infection (1 paper, 2014). "In the present study, I explored the functions of SRF and its representative cofactors, megakaryoblastic leukemia 1/2 (MKL1/2) and ETS-domain protein 4 (ELK4), during fungal infection challenge in macrophages." (PMID 24758171, 2014).
glioma (1 paper, 2021). A benign or malignant brain and spinal cord tumor that arises from glial cells (astrocytes, oligodendrocytes, ependymal cells). "The expression of ELK3, ETV4, and to some extent ELK4 was found to increase gradually with glioma grade, while ETV1 expression was highest in grade 2 glioma, and progressively decreased with glioma stage." (PMID 33671331, 2021).
lymphopenia (1 paper, 2018). Reduction in the number of lymphocytes. "Elk4-null mice are defective in thymocyte positive selection and exhibit lymphopenia, which can promote differentiation of memory-like CD8+ T cells in the periphery." (PMID 30068599, 2018).
mastocytosis (1 paper, 2023). A clonal myeloproliferative neoplasm characterized by the proliferation and accumulation of neoplastic mast cells in one or multiple organs or organ systems. "In this study, we established the important role of ELK4 in regulating mast cell proliferation but not mast cell development, which may impact disorders related to mast cell proliferation, such as mastocytosis." (PMID 37529050, 2023).
renal carcinoma (1 paper, 2021). A carcinoma arising from the epithelium of the renal parenchyma or the renal pelvis. "On a similar note, a significant association between the expression of ELK4, CBFB, IFI16, PRRX1, AEBP1, and GATA3 with an unfavourable outcome in renal cancer has been identified in previous reports." (PMID 35201514, 2021). "For instance, ELK4, CBFB, IFI16, PRRX1, AEBP1, and GATA3 expression was associated with an unfavourable outcome in renal cancer revealing the significance of these TFs (pink and blue colours represent unfavourable and favourable prognosis, respectively)." (PMID 35201514, 2021).
Williams-Beuren syndrome (1 paper, 2015). "Such functions are also known for the genes that are ECpiC loci, such as the oncogenic transcription factors ABL2 and ELK4, the miRNA effector AGO2, and TBL2 and KCTD7 genes that are in the deleted locus of Williams-Beuren syndrome patients, which display developmental defects." (PMID 26588211, 2015).